SDHB (succinate dehydrogenase complex iron sulfur subunit B)
Diseases named in the same sentence as SDHB in open-access papers (continued):
Sharing a sentence is not in itself a finding about the gene and the disease.
thyroid cancer (5 papers, 2014 to 2019). "Meanwhile, in sporadic thyroid cancers, about 6% of patients showed germline mutation of SDHB or SDHD." (PMID 31817761, 2019). "Germline variants in SDHB/C/D (SDHx) genes account for subsets of CS/CS-like cases, conferring a higher risk of breast and thyroid cancers over those with only germline PTEN mutations." (PMID 25694510, 2015). "Thus, there was an overall 6% prevalence of germline SDHB/D variants in the combined datasets comprising 754 thyroid cancer patients compared with 0/350 of our residential population controls (P<0.001)." (PMID 25694510, 2015). "Taken together, our studies suggest that upregulation of miR-96-3p promotes tumor invasion and metastasis of thyroid cancer via regulating the SDHB/AKT/mTOR pathway." (PMID 31749660, 2019). "To further verify the downstream molecular mechanism of the miR-96-3p/SDHB in metastasis in thyroid cancer, we focused on the AKT/mTOR pathway, which has been proved to be cellular biological function of the cancer." (PMID 31749660, 2019). "We found germline SDHB/D variants in ∼10% of PTEN mutation negative CS/CSL, associated with increased thyroid carcinoma prevalence compared with those with only germline PTEN mutations." (PMID 25149476, 2015).
adrenal pheochromocytomas (4 papers, 2010 to 2023). "Genetic disorders involving mutations within the succinate dehydrogenase B and D units (SDHB, SDHD) and the von Hippel-Lindau (VHL) gene places an increased risk in the development of extra-adrenal paragangliomas and adrenal pheochromocytomas, respectively." (PMID 21188160, 2010).
adrenal tumor (4 papers, 2020 to 2025). "Specifically, having a previous history of PPGLs, presenting a large tumor volume, elevated levels of MTY and NMN, extra-adrenal tumor location, and the presence of SDHB mutations all contribute to higher predicted probabilities of metastasis." (PMID 40648440, 2025). "Limitations: In our study, we had a large number of consecutive cases, but the majority were adrenal tumors and a small number were extra-adrenal tumors which are usually have the SDHB mutation." (PMID 38667494, 2024).
Bladder Paraganglioma (4 papers, 2020 to 2024). A benign or malignant extra-adrenal sympathetic paraganglioma arising from the urinary bladder. "A study conducted in London on patients with bladder paraganglioma found pathogenic SDHB variants in 6/9 individuals, again mostly in male and younger individuals." (PMID 33308260, 2020). "In the few Asian genetic studies on urogenital paragangliomas, SDHB exon 7 deletion was reported in an Indian patient with bladder paraganglioma, while SDHB: c.112delC (p.Arg38fs) variant was reported in a Hong Kong Chinese patient with recurrent metastatic bladder paraganglioma." (PMID 33308260, 2020). "The result of postoperative pathology was immediate-risk functional bladder paraganglioma (T2N0M0, Stage II) concomitant with urothelial papilloma, and the immunohistochemistry results of PPGL were positive for Ki-67 (15%), SDHB, CgA, and SSTR2." (PMID 36741690, 2023).
gastric cancer (4 papers, 2018 to 2022). A primary or metastatic malignant neoplasm involving the stomach. "In line with our findings, brain tumors have previously been reported in gastric cancer families with causative germline alterations in CDH1 and other (suspected) tumor suppressor genes, e.g. ATM, CTNNA1, and SDHB." (PMID 33929593, 2021).
gastric tumors (4 papers, 2013 to 2025). "Four of these tumors were SDHB-deficient GISTs, which have been well characterized as gastric tumors with multinodular epithelioid morphology and an indolent clinical course." (PMID 24133624, 2013). "The sporadic adult SDHB-negative GISTs in both studies were gastric tumors of epithelioid morphology." (PMID 23730622, 2013).
glioma (4 papers, 2015 to 2024). A benign or malignant brain and spinal cord tumor that arises from glial cells (astrocytes, oligodendrocytes, ependymal cells). "By analyzing The Cancer Genome Atlas (TCGA) data, we found that OGDH mRNA levels were significantly downregulated in IDH-mutated gliomas compared with other TCA cycle enzymes, including citrate synthase (CS), succinate dehydrogenase complex subunit B (SDHB), and fumarate hydratase (FH)." (PMID 39872214, 2024). "Our results show that in CNS WHO grade 1 glioma samples there is no overexpression of SDHB, meanwhile the samples of CNS WHO grade 2 showed an expression level of 1.7 and 5.7-fold, and CNS WHO grade 3 and 4 samples showed overexpression of 2.6 to 7.47-fold." (PMID 34573317, 2021). "In contrast, expression levels of enzymes involved in downstream metabolism of isocitrate, including IDH1, IDH2 and IDH3A, α-KGDH, succinate dehydrogenase (SDHB), fumarate hydratase (FH) and malate dehydrogenase (MDH2), were remarkably lower in IDH1MUT glioma versus IDH1WT glioma." (PMID 28467784, 2017). "Finally, the Krebs cycle and fatty acid synthesis pathways play central roles in cellular metabolism; we also found that the IDH1, SDHB, FASN, ACACA, and ELOV2 genes were overexpressed, resulting in significant disturbances in the cellular metabolism of gliomas." (PMID 34573317, 2021). "With respect to the SDHB gene, we found that in CNS WHO grade 1 glioma it was not overexpressed." (PMID 34573317, 2021).
kidney cancer (4 papers, 2017 to 2025). Primary or metastatic malignant neoplasm involving the kidney. "In the present study, we confirmed enhanced susceptibility of SDHB-silenced kidney cancer cells to the BET inhibitor JQ-1." (PMID 28423651, 2017). "The loss of SDHB function is closely related with metabolic changes in kidney cancer cells." (PMID 34094922, 2021). "SDH-deficient RCC is likewise a relatively rare subset of kidney cancers but has been associated with germline PVs in both SDHA and SDHB." (PMID 38770192, 2024).
Leigh syndrome (4 papers, 2020 to 2025). A progressive neurological disease defined by specific neuropathological features associating brainstem and basal ganglia lesions. "Variants associated with Leigh syndrome retained activity, consistent with their biallelic inheritance and distinct pathogenic mechanisms from SDHB-related tumorigenesis." (PMID 41252211, 2025). "Currently, the homozygous sdhb zebrafish larvae possess resemblance to patients with bi-allelic SDHB mutations with a Leigh-syndrome-like phenotype, resulting in severe progressive neurodegeneration and myopathy with the onset in infancy and poor prognosis." (PMID 34680273, 2021). "The two main phenotypes associated with Complex II-encoded genes, SDHA, SDHB, SDHD, and the assembly factor SDHAF1 are associated with progressive encephalopathy leukodystrophy, Leigh syndrome, and/or cardiomyopathy." (PMID 33426505, 2020).
leukemia (4 papers, 2007 to 2023). A malignant (clonal) hematologic disorder, involving hematopoietic stem cells and characterized by the presence of primitive or atypical myeloid or lymphoid cells in the bone marrow and the blood. "If the somatic SDHB mutations are proven to play a role in oxygen homeostasis in PBMCs and leukemic T cells, targeting of the SDH complex might provide new therapeutic tools against infections, leukemia and cancer." (PMID 17487275, 2007).
lung adenocarcinoma (4 papers, 2015 to 2025). A carcinoma that arises from the lung and is characterized by the presence of malignant glandular epithelial cells. "To further understand the association of CDA gene expression with SDHB c.136C>U RNA editing, we evaluated RNA sequencing data in the Cancer Genome Atlas (TCGA) for three randomly chosen cancers, primary head and neck squamous cell carcinoma, lung adenocarcinoma and secondary skin cutaneous melanoma." (PMID 25898173, 2015). "Additionally, tissue microarrays containing samples derived from lung adenocarcinoma showed a correlation between eIF5A1 and Ki67 positive cells and SDHB, suggesting potential sensitivity in this context." (PMID 41390489, 2025). "Finally, survival analysis using Kaplan-Meier (KM) estimates indicated that elevated SDHB expression was correlated with a shorter five-year survival rate in 718 lung adenocarcinoma patients (HR = 1.53, p < 0.000)." (PMID 35127502, 2021).
Lynch syndrome (4 papers, 2019 to 2025). An autosomal dominant hereditary neoplastic syndrome characterized by the development of colorectal carcinoma and a high risk of developing endometrial carcinoma, gastric carcinoma, ovarian carcinoma, renal pelvis carcinoma, and small intestinal carcinoma. "Four patients (36%) had a germline mutation; two had paraganglioma syndrome type 4 (SDHB), one had a paraganglioma syndrome type 1 (SDHD), and one had Lynch syndrome (PMS2)." (PMID 32824391, 2020).
malignant pheochromocytoma (4 papers, 2018 to 2024). "The main prognostic factors of the malignant pheochromocytomas are a large tumor volume, the existence or number of visceral metastases, and the presence of a mutation in the SDHB (Succinate dehydrogenase B) gene." (PMID 34052712, 2021). "Intriguingly, there are few reports of malignant pheochromocytoma patients harboring SDHB mutations with prolonged survival." (PMID 29768630, 2018). "The absence of mutations in the reported case, especially SDHB, may also be related to long-term survival, since SDHB mutations are independently related to shorter survival in patients with malignant pheochromocytoma." (PMID 29768630, 2018). "Among them, miR-101 and miR-183 significantly differed in SDHB mutant vs. wild type samples and interestingly, miR-483-5p had significantly lower expression in SDHB mutant malignant pheochromocytoma compared to all other malignant pheochromocytomas." (PMID 33810219, 2021).
melanoma (4 papers, 2005 to 2020). A malignant, usually aggressive tumor composed of atypical, neoplastic melanocytes. "Significantly, MITF depletion using two different MITF‐specific siRNAs led to reduced SDHB expression in two melanoma cell lines." (PMID 31207090, 2019). "Since MITF controls transcription, we first examined whether the mRNA expression of the key SDH subunit SDHB correlated with the pseudo‐hypoxic signature in the CCLE melanoma cell lines." (PMID 31207090, 2019). "As such, the low levels of SDHB in MITF‐low cells may contribute to disease progression in melanoma." (PMID 31207090, 2019). "Similar dose-dependent downregulation of NDUFB8, SDHB/Ip, and UQCR2 was also observed in the case of WM983-B melanoma cells (data not shown)." (PMID 22912665, 2012).
multiple endocrine neoplasia (4 papers, 2018 to 2023). Multiple endocrine neoplasia (MEN) is a group of rare inherited cancer syndromes characterized by the development of two or more endocrine gland tumors, sometimes with tumor development in other tissues or organs. "Examples of PPGLA mutations include the RET gene in multiple endocrine neoplasia (MEN) syndromes, the VHL gene in von Hippel–Lindau disease, the NF1 gene in Neurofibromatosis type 1, the MAX gene, or the genes of the succinate dehydrogenase complex (SDHB, SDHD, SDHA, SDHC, SDHAF2)." (PMID 36010170, 2022).
renal tumor (4 papers, 2020 to 2024). "SDHB-deficient renal tumor cells displayed a marked change in their energetic metabolism with a shift to aerobic glycolysis and marked decrease of oxidation phosphorylation, with very low entry of glucose into TCA cycle metabolites." (PMID 32751108, 2020). "The number of genes within a panel may be as few as six (e.g. BAP1, FH, FLCN, MET, SDHB, and VHL genes) though commercial genetic testing companies may offer larger gene panels (18–30 genes but including some for non-RCC kidney tumours;)." (PMID 38802529, 2024).
sarcoma (4 papers, 2020 to 2025). A usually aggressive malignant neoplasm of the soft tissue or bone. "The proposed three-tier scoring system for SDHB staining provides a newly developed tool to categorize SDH expression levels in sarcoma tissues, complementing transcriptomic findings and offering a potential biomarker for future studies." (PMID 41081835, 2025).
thyroid tumor (4 papers, 2015 to 2023). A benign or malignant neoplasm affecting the thyroid gland. "As a pilot, we initially checked the SDHB/C/D mRNA expression in our 37 paired sporadic thyroid tumor-normal tissue samples (seven FTC and 30 PTC)." (PMID 25694510, 2015). "SDHB protein expression has not been examined in sporadic differentiated thyroid tumors by immunohistochemistry yet and it will be interesting to correlate protein expression with its gene expression." (PMID 25694510, 2015).
atherosclerosis (3 papers, 2022 to 2023). A disease characterized by the build-up of fatty material and calcium deposition in the arterial wall resulting in partial or complete occlusion of the arterial lumen. "TMAO accelerated in vivo and in vitro VEC pyroptosis.TMAO induced mitochondrial damage and promoted ROS production.TMAO upregulated SDHB expression of VECs in vitro and in vivo that is involved in TMAO-induced atherosclerosis." (PMID 37337893, 2023).
cardiomyopathy (3 papers, 2020 to 2025). A disease of the heart muscle or myocardium proper. "There is phenotypic heterogeneity associated with the c.143A>T p.(Asp48Val) SDHB variant, with reported presentations including leukodystrophy, psychomotor regression and cardiomyopathy." (PMID 33162331, 2020). "Interestingly, changes in FGF21-responsive genes such as OXCT1, the SUCL complex, PDHA1, OGDH, ACO2, IDH3B, and ETC components (MT-CO2, COQ9, UQCRQ, SDHB/D and NDUFB7) are linked to mitochondrial deficiency syndromes manifesting cardiomyopathy and encephalopathy." (PMID 40998786, 2025).
carotid body paraganglioma (3 papers, 2021 to 2025). A benign or malignant extra-adrenal parasympathetic paraganglioma arising from paraganglia adjacent to or in the bifurcation of the common carotid artery. "Out of the 24 patients, 9 (37.5%) carried pathogenic variants (2 SDHB, 7 NF1) and in one patient a novel VHL variant, classified as VUS was detected (VHL: p.36_37insSGPEE) in a young patient presenting with carotid body paraganglioma." (PMID 34439371, 2021).
leiomyoma (3 papers, 2014 to 2025). A well-circumscribed benign smooth muscle neoplasm characterized by the presence of spindle cells with cigar-shaped nuclei, interlacing fascicles, and a whorled pattern. "In the second leiomyoma, SDHB immunohistochemical expression was retained, appearing slightly stronger than in the first one." (PMID 38793008, 2024). "The first leiomyoma exhibited a specific dot-like immunostaining pattern for the SDHB antibody." (PMID 38793008, 2024).
lymph node metastasis (3 papers, 2013 to 2025). "In addition, half of the SDHB-deficient GIST patients in the study cohort developed lymph node metastases, which is consistent with the results of previous studies." (PMID 41105177, 2025). "Genetic testing was performed on 45 patients in the lymph node metastasis group, and 33 patients (73.3%) had KIT gene mutations, including 25 patients with KIT 11 mutations and 9 patients with KIT 8 mutations; 12 patients (26.7%) had wild-type GIST, of whom 4 patients had SDHB-deficient GIST." (PMID 41105177, 2025).
papillary thyroid cancer (3 papers, 2018 to 2020). "However, the mechanism of SDHB associated with the papillary thyroid cancer is poorly understood." (PMID 31749660, 2019). "Identification of two of these actionable variants (RBM20 and SDHB) led to screening that identified associated findings (evidence of DCM and papillary thyroid cancer, respectively) and may have a significant impact on these participants’ long-term health." (PMID 30487145, 2018).
T-cell acute leukemia (3 papers, 2007 to 2021). "In this report, I demonstrate that the SDHB subunit gene is targeted by a somatic mutational mechanism in normal peripheral blood and childhood T-cell acute leukemia." (PMID 17487275, 2007). "Here, I describe that succinate dehydrogenase (SDH; mitochondrial complex II) subunit B gene (SDHB) is somatically mutated at a cytidine residue in normal peripheral blood mononuclear cells (PBMCs) and T-cell acute leukemia." (PMID 17487275, 2007). "Transcript sequence analyses in leukemic cell lines derived from monocyte, NK, T and B cells indicate that the mutational mechanism targeting SDHB is operational in T-cell acute leukemia." (PMID 17487275, 2007). "Accordingly, substantial levels (more than 3%) of the mutant SDHB transcripts are detected in five of 20 primary childhood T-cell acute lymphoblastic leukemia (T-ALL) bone marrow samples, but in none of 20 B-ALL samples." (PMID 17487275, 2007).
acute myeloid leukemia (2 papers, 2023 to 2025). Acute myeloid leukemia (AML) is a group of neoplasms arising from precursor cells committed to the myeloid cell-line differentiation. "In acute myeloid leukemia, downregulation of SDHB sensitized leukemia cancer cells to BCL-2-inhibitor-induced apoptosis, which may explain the specific anti-tumor effect of the BCL-2 inhibitors towards high OTX2-AS1 expressing cells in medulloblastoma." (PMID 37976029, 2023).
adrenal adenoma (2 papers, 2017 to 2022). "Three SDHB mutation carriers (3 %) had a non-hypersecreting adrenal adenoma, either based on the pathology report (n = 1), or based on MRI and scintigraphic findings in combination with normal levels of plasma metanephrines (n = 2)." (PMID 27573198, 2017).
anemia (2 papers, 2019). A reduction in the number of red blood cells, the amount of hemoglobin, and/or the volume of packed red blood cells. "Renal failure which required final dialysis occurred in one patient with SDHB in whom we also observed G3 anemia." (PMID 31262070, 2019).
bladder tumours (2 papers, 2019 to 2021). "PGL should be included in the differential diagnosis of bladder tumours, and testing for SDHB gene mutations should be considered in all urinary PGLs." (PMID 34567891, 2021). "One SDHB mutation carrier with a urinary bladder tumor and bone metastases had only a single PRRT treatment session and then developed a pathological spine fracture, which led to tetraplegia." (PMID 31262070, 2019).
bone metastasis (2 papers, 2025). Transfer of a neoplasm from its primary site to bones. "In a retrospective multicenter, multinational study, patients with SDHB mutations were more likely to develop bone metastasis." (PMID 41306434, 2025). "In this paper, we present a case that initially presented with FUO, and was ultimately diagnosed with HNPGLs with multiple metastases, accompanied by special imaging findings of bone metastasis, an SDHB pathogenic variant, and a KIF1B variant of uncertain significance." (PMID 40917352, 2025).
breast tumors (2 papers, 2013 to 2015). "The SDHA/SDHB expression phenotypes in these 712 breast tumors were, in order of frequency, SDHA(+)/SDHB(+) > SDHA(-)/SDHB(–) > SDHA(-)/SDHB(+) > SDHA(+)/SDHB(–)." (PMID 23888270, 2013).
differentiated thyroid carcinoma (2 papers, 2015 to 2020). Differentiated thyroid carcinoma (DTC), also known as papillary or follicular thyroid carcinoma, is a slow-growing malignancy usually presenting in adults as an asymptomatic thyroid mass. "When our pilot of 48 apparently sporadic DTC samples revealed germline variation in SDHB and SDHD, we expanded our series to a total of 241 unrelated PTEN mutation negative research participants with differentiated thyroid carcinoma from The Ohio State University's (OSU) Thyroid Center." (PMID 25694510, 2015).